CTNNB1 (catenin beta 1)
Diseases named in the same sentence as CTNNB1 in open-access papers (continued):
Sharing a sentence is not in itself a finding about the gene and the disease.
cancer (continued). "In addition, cancers with alterations in RNF43, CTNNB1, and TCF7L2 displayed high rates of mutations in receptor tyrosine kinases, MMR-associated genes and DDR-associated genes, independently of the presence or absence of concomitant APC alterations." (PMID 40061138, 2025). "Besides IL-6, cancer cell–secreted Wnt5a induces IDO1 expression through β-catenin (CTNNB1) activation in DCs." (PMID 40789452, 2025). "However, of those genes included in the pPRS score, prior evidence links NSAIDs anti-cancer activity with β-catenin (CTNNB1), GNAS, and PTGER4, the extracellular receptor for PGE2 that is the major downstream prostanoid produced by PTGS-2." (PMID 40763299, 2025). "The direct role of HuR-dependent stabilization of CTNNB1 mRNA could prove to be a powerful tool for understanding many cancers with overlapping HuR expression and Wnt signaling activation." (PMID 41516083, 2025). "We suspect that DOT1L may affect WNT signaling by influencing expression of CTNNB1 and promote the formation of cancer stem cells by promoting CD44 expression." (PMID 38495505, 2024). "Sinapic acid is a potent anti-oxidant used for the treatment of cancer, infections, oxidative stress, and inflammation; its anti-cancer mechanism works through the regulation of multiple proteins (CTNNB1, PRKCA, CASP8, SIRT1) and cytochrome enzymes (CYP1A1, CYP3A4)." (PMID 38999065, 2024). "Moreover, changes in the cancer methylome are coupled with somatic mutations in cancer driver genes, such as CTNNB1, ERBB2, KRAS, and PIK3CA, which consistently recapitulate the somatic evolutionary process and consequential clonality of cancers." (PMID 38566132, 2024). "Four genes, RAB10, KLF5, TCF7L2, and CTNNB1 had gene essentiality strongly correlated with both SMAD4 mutation and SMAD4 CNA in various cancer cells (i.e., genes that are more essential when SMAD4 copy number is decreased or when SMAD4 is mutated, P values inferior to 1E-04)." (PMID 37377893, 2023). "The most prevalent altered cancer-related genes were CTNNB1 (16%) and ZNRF3 (16%)." (PMID 38023213, 2023). "Most CTNNB1-related studies have been mainly focused on its role in cancer." (PMID 37009120, 2023). "According to this research, CBX2 could control CEP55 or CTNNB1 to control the characteristics of cancer stem cells that are consistent with more aggressive migration." (PMID 37980163, 2023). "Deubiquitylation of CTNNB1 has also been detected in cancers." (PMID 37740194, 2023). "Aberrant CTNNB1 signaling frequently occurs in cancers, particularly colorectal cancer (CRC)." (PMID 36646695, 2023). "In this study, the most prevalent altered cancer-related genes were CTNNB1 (16%) and ZNRF3 (16%)." (PMID 38023213, 2023). "In addition, these four cancer pathways were jointly enriched in four genes, CTNNB1, TCF7L2, NRAS, and KRAS, mainly involved in cell proliferation." (PMID 36399471, 2022). "Aberrant CTNNB1 signaling is one of the fundamental processes in many human cancers." (PMID 36499305, 2022).
cancer (continued). "However, CTNNB1 and BRAF mutations are consistently overrepresented in AYAs across multiple cancer types." (PMID 36433963, 2022). "APC, CTNNB1, AXIN1, FAM123B, and TCF7L2 are the key molecules in Wnt signaling pathway that may undergo somatic mutations related to common human cancers, including colon cancer." (PMID 36142412, 2022). "Thus, it appears likely that the downregulation of KCTD9 occurs independently of such mutations and the effects of KCTD9 on β-catenin expression would still be relevant in APC and/or CTNNB1 mutant cancers." (PMID 36055981, 2022). "Emerging studies show that circRNA catenin beta 1 (circCTNNB1) plays a critical role in cancer." (PMID 35435123, 2022). "In most human cancers, inactivation of the β-catenin destruction complex via mutation or promoter methylation of the APC and Axin genes is far more common than activating mutations of the β-catenin gene CTNNB1." (PMID 36428715, 2022). "To assess the performance of this screening platform, we began with β-catenin, a key hub in the Wnt signaling pathway that is an attractive intracellular target for therapeutic intervention in the many Wnt-driven cancers, such as those with APC or CTNNB1 mutations." (PMID 36534810, 2022). "For instance, alterations in the CTNNB1 and APC genes can lead to activation of the Wnt signaling pathway, whereas activating GNAQ mutations can lead to Hippo-independent activation of YAP pathways and cancer progression." (PMID 36497457, 2022). "However, LINC00589 also interacts with HUR and stabilizes CTNNB1 mRNA, thereby promoting cancer progression in pancreatic cancer." (PMID 36309503, 2022). "have recently addressed that the Wnt/β-catenin signaling pathway is activated, particularly by CTNNB1 mutation, in non-T cell-inflamed tumors across cancer types including HCC13." (PMID 34429454, 2021). "Interestingly, TRIM6 expression was positively correlated with several cancer-related pathways, including NF-κB, CTNNB1, and STAT3 signaling." (PMID 34589421, 2021). "Nevertheless, genomic amplification of the CTNNB1 gene, which might also be a mechanism for overexpression of the protein in cancer in humans, cannot completely be excluded." (PMID 34885050, 2021). "In order to further determine the function of two candidate genes CTNNB1 and KMT2D, and locate potential cancer-associated genes that may play a key role in cell proliferation, we used an short hairpin RNA (shRNA)-mediated loss-of-function screening method." (PMID 33968779, 2021). "In our cohort, cancers in women with CTNNB1 mutations did not have worse survival outcomes, but the average age of these women was less than that of the overall cohort (49 years compared to 59 years)." (PMID 34830795, 2021). "As a result, the CTNNB1 mutations or fusion genes were independent negative predictive factors in multivariate analysis despite the resected small size cancers." (PMID 33140254, 2021). "The correlation between CTNNB1 somatic mutations and MLH1 germline mutations was confirmed in another study, which suggested that MLH1-mutant cancers may develop from MMR-deficient crypt foci (MMR-DCF)." (PMID 33923068, 2021).
cancer (continued). "Furthermore, our study screened a set of cancer cell genes in different stemness-related signaling pathways, including CTNNB1, SOX6, and CD133 in CCA, to show that stemness genes were targeted by m6A modification." (PMID 34347395, 2021). "The first is the conceptual notion that, even in the absence of apparent mutations, WNT/CTNNB1 plays a central role in the maintenance of multiple adult tissue stem cell populations and, by analogy and extension, in cancer stem cells." (PMID 32083079, 2020). "In these extracolonic cancers, however, the computational method did not reveal homozygous CTNNB1 mutations." (PMID 33115416, 2020). "For category 1, we identified a significant correlation of CCNE2-FOXM1 (10 cell line lineages, 17 patient cancer types) in cell cycle CTNNB1-SERPINE1 (eight cell line lineages, 17 patient cancer types) in EMT, and RB1-RPS6 (eight cell line lineages, 20 patient cancer types) in TSC/mTOR pathways." (PMID 32374631, 2020). "As shown by the colony formation and MTT assay results, overexpressing circXPO1 in A549 cells stimulated cancer cell proliferation, and the proliferative advantage conferred by circXPO1 overexpression was partially reversed by CTNNB1 silencing and IGF2BP1 silencing." (PMID 33268793, 2020). "However, there are some studies reporting that CTNNB1: rs1880481 has the opposite effect on other cancers." (PMID 32453708, 2020). "Some oncogenes such as MET and CTNNB1 showed slight overall negative enrichment, but their nonsynonymous mutations, especially in specific cancers, showed enrichment during periods of positive growth." (PMID 32024824, 2020). "In the case of CTNNB1, none of the positions under selection overlapped with the cancer mutated region." (PMID 32731489, 2020). "However, these CRC cells also contain mutations in other cancer related genes (HCT116: KRAS, PIK3CA, CTNNB1, BRCA2, CDKN2A etc.; SW480 or SW620: KRAS and APC etc.), which constitute a unique pathological context in every CRC cell." (PMID 32388500, 2020). "Of which, 660 genes were well-known cancer genes, such as CTNNB1, IDH1." (PMID 33240890, 2020). "We are tempting to speculate that our findings open a room for cancer researcher through a functional interplay between CTNNB1, GSK3, and TrCP1." (PMID 31699039, 2019). "Finally, module 4 included the genes PLCB4, MMP1, CTNNB1, EGF, F2R, and LPAR4, associated with pathways in cancer, Rap1 signalling pathway, and phospholipase D signalling pathways." (PMID 31178673, 2019). "Notably, for all the seven HUB nodes of the linking region between three cancer networks, mutations were found in all three cancers (BlC, KiC, PrC) with the higher frequency percentages identified for four nodes: MAP3K7, NR3C1, PABPC1 and CTNNB1." (PMID 29991691, 2018). "Additionally, an IPA analysis of possible upstream regulators of the differentially expressed proteins yielded a mechanistic network regulated by HNF1A (TCF1) and CTNNB1, a well-known cancer regulatory hub important for the Wnt signaling pathway." (PMID 29515771, 2018). "On the other hand, CTNNB1 resulted as a new HUB node in this analysis suggesting that it plays an important role in linking the three cancer networks and, hence, could be involved in the arsenicals- induced cancer development and progression." (PMID 29991691, 2018).
cancer (continued). "The hyperexpression of WNT target genes corresponds with the hyperactivated WNT pathway in primary CRC and CRC cancer cell lines, most likely resulting from the biallelic inactivation mutation of APC, FBXW7, AXIN2, and FAM123B or the activating mutations in CTNNB1." (PMID 30363662, 2018). "Any insight would be important for any cancer type that CTNNB1 or MDM4 plays a physiological role." (PMID 29362363, 2018). "However, the underlying mutations are different between species; activating CTNNB1 mutations are frequently observed in human HCC samples, while loss-of function mutations in Apc were found in mouse DEN carcinomas." (PMID 29958939, 2018). "Firstly, the co-expression patterns (log2-scale) between TUG1 and β-catenin (CTNNB1) in TCGA Pan-Cancer (PANCAN) showed that the expression of TUG1 was positively related to the expression of β-catenin, with a Pearson coefficient r = 0.1137 and P = 0.0189 (two tail, t-test) in 426 BUC samples." (PMID 29179467, 2017). "APC and CTNNB1 also displayed predominantly negative associations in two different cancer types each." (PMID 29125844, 2017). "SNP rs713065(C) in the miR-204 binding site in the FZD4 3′UTR might shed light on targeting at Wnt-CTNNB1 signaling anti-cancer treatment." (PMID 28831115, 2017). "Furthermore, the SNVs in CTNNB1, PIK3CA, PTEN and ESR1 were annotated in COSMIC, the catalogue of somatic mutations in cancer." (PMID 28103826, 2017). "For example, search of the Cancer Cell Line Encyclopedia revealed that HUH6 and SNU398 harbor somatic activating mutations in CTNNB1/β-catenin, while HepG2 carries a deletion in exons 3–4 of CTNNB1/β-catenin gene resulting in the deletion of amino acids 25–140." (PMID 29383099, 2017). "We found that, for each gene, over 95% of primary carcinomas across anatomic sites had no CDH1 or CTNNB1 mutations, as well as low prevalences of carcinomas with at least one mutation for the large majority of individual sites." (PMID 29156750, 2017). "However, evidence has shown that the effects of Wnt/CTNNB1 signaling are context-specific, and it can either promote or inhibit cancer progression." (PMID 27333864, 2016). "In addition to Nanog, other stemness genes including Notch2, CTNNB1 and Hsp90B1 are also important to CSCs and cancer cells." (PMID 27917123, 2016). "Furthermore, miR-150 directly down-regulated the expression of other cancer stem cell factors including Notch2 and CTNNB1." (PMID 27917123, 2016). "The series of different Apc and Ctnnb1 mouse models that we employed have previously been used to show that β-catenin activity levels are selected for by different types of cancer, and these ectopic increases in signalling activity can also lead to a range of developmental defects." (PMID 25647637, 2015). "Although, CTNNB1 activation is a canonical driver mutation, a decrease in normal levels of CTNNB1 may also be advantageous to cancer cells as RNAi depletion of CTNNB1 has been shown to increase cell migration." (PMID 24498085, 2014). "Recent studies have shown that CTNNB1 could regulate Tert expression through the interaction with Klf4, and thereby telomere length, which could be critical in human cancer." (PMID 24465727, 2014).
cancer (continued). "Instead, the Pathways in cancer genes Kras, Met, Figf, Hgf, Fgf7, Ctnnb1 and Tcf7l1, and directly interacting genes Nr3c2 and Csnk2a1 may lead to new insights in US28-mediated signaling and ultimately the oncomodulatory role of HCMV." (PMID 25002203, 2014). "Point mutations at exon 3 of CTNNB1 gene have been found in 25% of poorly differentiated carcinomas and 66% of ATCs, respectively, but not in well-differentiated carcinoma." (PMID 24868250, 2013). "Dysregulation of the canonical Wnt signaling pathway—via disrupted function of genes such as adenomatous polyposis coli (APC), AXIN1, β-catenin (CTNNB1), and secreted frizzled-related proteins (SFRPs)—has been noted for a variety of cancer types, including oral malignancies." (PMID 22645611, 2012). "Similarly to the regulation of cancer cell proliferation, TC adhesion and junction functions during placental development may be regulated by CTNNB1 and CDH1." (PMID 40150405, 2025). "Additionally, the discovery of synthetic lethality involving Wnt signaling suggests that CTNNB1-mutant cancers may be vulnerable to combination therapies targeting other pathways that intersect with Wnt signaling, such as the PI3K/AKT/mTOR pathway." (PMID 40072110, 2025). "In addition, the TGFbeta node was split into two nodes, namely TGFbeta_i (activated by NICD and inhibited by CTNNB1) and TGFbeta_e (activated by ECMicroenv), to differentiate between autocrine- and paracrine-TGFβ-related regulation of the cancer cell signaling, respectively." (PMID 41258301, 2025). "Hence, CTNNB1 was predicted to be down-regulated which may be one of the mechanisms by which sinapic acid prevents the progression of cancer." (PMID 38081857, 2023). "Notably, CTNNB1 3′ UTR splicing is the most consistently dysregulated event across cancers." (PMID 35618746, 2022). "The seven prevalent ‘candidate genes’ (ADAM10, ADAM17, AKT1, CTNNB1, ESR1, FGFR1, PIK3CA) showed direct associations with enriched terms under the categories of ‘Neurodegenerative disorders’, ‘Neurodevelopmental diseases’, ‘CNS tumour/cancer’ and ‘Cellular Signaling pathways’." (PMID 36229517, 2022). "Consistently, we found that several downregulated genes associated with cancer cells metabolism (Pfkfb3, Fgfbp1, Gnas, Pfkfb4, Ctnnb1, and Tsta3) in the colon of EgPSC-infected mice, indicating that intraperitoneally EgPSC infection may elicit protective effect in cancer development." (PMID 36713407, 2022). "Numerous studies have shown that CTNNB1, the gene of beta-catenin, together with APC and Axin are frequently mutated in different types of human cancers and that the nuclear accumulation of beta-catenin could be considered the final step of constitutive activation of WNT signaling." (PMID 35463299, 2022). "Additionally, cancers driven by the WNT/CTNNB1 pathway exhibit a unique immune signature that may be susceptible to inhibition by immune therapies." (PMID 31941061, 2020). "However, the Chi-squared test χ2 revealed, after exclusion of gender-specific cancer diseases, five different genetic mutations that are significantly more common in men than in women: CDKN2A (p = 0.04), CTNNB1 (p = 0.002), KIT (p = 0.0005), SLX4 (p = 0.034), and VHL (p = 0.046)." (PMID 33114048, 2020).